HIF1A (hypoxia inducible factor 1 subunit alpha)
Diseases named in the same sentence as HIF1A in open-access papers (continued):
Sharing a sentence is not in itself a finding about the gene and the disease.
acanthamoebiasis (1 paper, 2024). "In our novel study, we analyzed HIF1α and HIF2α by molecular, immunoenzymatic as well as immunohistochemistry methods in the kidneys of hosts with systemic acanthamoebiasis." (PMID 39543383, 2024). "The exact role of HIF1α and HIF2α in infectious diseases, including acanthamoebiasis, remains unknown." (PMID 39543383, 2024). "We speculate that the activation of HIF1α and/or HIF2α in the kidneys of hosts with acanthamoebiasis might also be induced via NOX2/ROS." (PMID 39543383, 2024).
acne (1 paper, 2023). An inflammatory process of the sebaceous glands which is characterized by comedones, nodules, papules and/or pustules on the skin. "Surprisingly, there are no data on the effect of benzoyl peroxide, the most commonly used topical anti-acne agent, on ductal HIF-1α expression in skin with acne." (PMID 37998335, 2023). "Azelaic acid, another anti-acne agent used topically, might also interfere with HIF-1α because it is known to inhibit anaerobic glycolysis." (PMID 37998335, 2023). "A pilot study indicated that the extraction of an acne lesion reduces HIF-1α expression." (PMID 37998335, 2023). "mTORC1 has a special impact in regulating the protein translation of specific transcription factors involved in the pathogenesis of acne, including SREBFs, PPARγ, STAT3 and hypoxia-inducible factor-1α (HIF-1α)." (PMID 37998335, 2023).
adenoid cystic carcinoma (1 paper, 2014). A malignant tumor arising from the epithelial cells. "In the present study, we explored the expression and correlation of survivin with HIF-1α, TGF-β1 and TFE3 in adenoid cystic carcinoma (AdCC)." (PMID 25485635, 2014).
adenovirus infection (1 paper, 2015). "In this study, we showed that overexpression of HIF-1α with adenovirus infection promoted EMT, cell invasion and migration in vitro and in vivo." (PMID 26057751, 2015).
Age-related cataract (1 paper, 2024). A type of cataract (opacification of the lens) that forms during the course of aging. "In age-related cataract, downregulation of Heat shock transcription factor 4 isoform b (HSF4b), which contributes to lens transparency maintenance, is believed to reduce HIF-1α levels, potentially causing cortical and nuclear cataracts." (PMID 38416732, 2024).
alcohol addiction (1 paper, 2021). "Considering that most LSCC patients possess cigarette and alcohol addiction, HIF-1α transcription might be a factor connecting glycolytic metabolism and immunotherapy, which is worthy of further validation." (PMID 34565301, 2021).
amebiasis (1 paper, 2024). A parasitic infectious disorder caused by amoebas. "Alterations to HIF1α expression and hypoxic-related signaling have been described during other protozoan parasitic infections, such as amebiasis, toxoplasmosis, and leishmaniasis." (PMID 39543383, 2024).
ampullary carcinoma (1 paper, 2024). "Moreover, including the presence of necrosis as a parameter in ampullary carcinoma reports may facilitate the evaluation of potential HIF1α-targeting or antiangiogenesis therapies that can be used in these patients." (PMID 38922490, 2024).
androgenetic alopecia (1 paper, 2023). "In this study, we demonstrated that hypoxia-inducible factor-1α (HIF-1α) is suppressed in scalp tissues of androgenetic alopecia patients and potentially associated with hair follicle development." (PMID 36707659, 2023). "In scalp tissues with androgenetic alopecia, which show progressive hair loss, HIF1A mRNA levels were significantly repressed compared to those in tissues from healthy individuals." (PMID 36707659, 2023). "Herein, we showed that HIF1A was downregulated in androgenetic alopecia (AGA) tissues and that HIF1A expression levels were positively correlated with hair inductivity-related genes by using informatic analysis." (PMID 36707659, 2023).
anterior uveitis (1 paper, 2025). Inflammation of the iris and anterior chamber of the eye. "Recent studies suggest that certain antioxidant and anti-inflammatory agents can reduce the severity of anterior uveitis by modulating HIF-1α and TNF-α signaling pathways." (PMID 41402737, 2025).
aortic valve disease (1 paper, 2019). "Studies have reported expression of hypoxia inducible factor-1 alpha (HIF1α) in calcific nodules in aortic valve disease, therefore we investigated the effect of hypoxia on extracellular matrix remodeling in aged aortic valves." (PMID 31737648, 2019).
ascorbic acid deficiency (1 paper, 2015). A condition due to a dietary deficiency of ascorbic acid (vitamin C), characterized by malaise, lethargy, and weakness. "Further studies to evaluate the causes of ascorbic acid deficiency and its role in the loss of HIF-1α regulation in malignancy are needed." (PMID 26547841, 2015).
Atrophy (1 paper, 2024). Any weakening or degeneration, especially through lack of use. "Shenshuai Yingyang Jiaonang has been shown to improve muscle atrophy associated with CKD-associated muscle atrophy in rats by inhibiting ferroptosis through the HIF-1α/SLC7A11 pathway." (PMID 39596528, 2024).
autonomic dysfunction (1 paper, 2023). "Overall, the combination of Hif1a deficiency and the diabetic environment had an adverse impact on the size of the sympathetic chain ganglia, including the stellate ganglia, which increases the risk of autonomic dysfunction." (PMID 37072781, 2023).
autosomal dominant hypophosphatemia (1 paper, 2016). "Recent studies have implicated the hypoxia-inducible factor-1α (HIF-1α) in other phosphate wasting disorders caused by elevated FGF23, including X-linked hypophosphatemic rickets and autosomal dominant hypophosphatemia." (PMID 27468359, 2016).
Barth syndrome (1 paper, 2018). Barth syndrome (BTHS) is an inborn error of phospholipid metabolism characterized by dilated cardiomyopathy (DCM), skeletal myopathy, neutropenia, growth delay and organic aciduria. "Tafazzin deficiency does not affect posttranslational HIF-1α regulation but rather HIF-1α gene expression, a dysfunction recapitulated in iPSC-derived cardiomyocytes from Barth syndrome patients with tafazzin deficiency." (PMID 30332638, 2018).
benign breast tumor (1 paper, 2016). "Both HIF-1α and PGC-1α plasma levels were significantly lower in benign breast tumor cohort, with a mean of HIF-1α plasma level 6.490ng/dl (95% CI 6.192-6.788), and 127.809ng/dl (95% CI 111.974-143." (PMID 27780920, 2016).
benign meningioma (1 paper, 2023). A grade I, slowly growing meningioma. "Overall, our findings suggest that in intracranial benign meningioma, genes of the AhR signaling pathway are involved in the adaptation to hypoxia in both HIF-1α-dependent and HIF-1α-independent manners." (PMID 37305351, 2023).
bile duct cancer (1 paper, 2017). "Previously, we demonstrated that PDT of human skin and bile duct cancer cells with liposomal ZnPC and acriflavine, an inhibitor of hypoxia-inducible factor 1α (HIF-1α), increases therapeutic efficacy by downmodulation of HIF-1α-driven survival signaling following PDT." (PMID 27803950, 2017).
bladder infections (1 paper, 2015). "The dynamics of HIF-1α expression has been studied in the context of bladder cancer; however, its role during bladder infections has not been explored." (PMID 25927232, 2015).
breast disease (1 paper, 2013). "Second, HIF-1α is an interesting therapeutic target at the pre-invasive stage of BRCA mutation-related breast disease to prevent invasive disease." (PMID 23409121, 2013).
breast luminal cancer (1 paper, 2020). "GRK2 also promotes the HuR/HIF-1α axis and VEGF-C accumulation in normoxic MCF7 breast luminal cancer cells and is required for the induction of HuR/HIF1-α in response to adrenergic stress." (PMID 32413989, 2020).
breast phyllodes tumor (1 paper, 2005). A benign, malignant, or borderline circumscribed biphasic neoplasm that arises from the breast. "This is the first report on HIF-1α and CAIX expression in breast phyllodes tumors." (PMID 16168127, 2005). "This is the first study evaluating HIF-1α and CAIX expression in breast phyllodes tumors." (PMID 16168127, 2005).
bronchiolitis (1 paper, 2021). Inflammation of the bronchioles characterized by swelling of the bronchioles and mucus accumulation. "Likewise, the role of HIF-1α in bronchiolitis is supported by experimental data on the consequences of HIF-1α stabilization by the Respiratory Syncytium Virus." (PMID 34621299, 2021).
bronchopneumonia (1 paper, 2017). Acute inflammation of the walls of the terminal bronchioles that spreads into the peribronchial alveoli and alveolar ducts. "In an immune competent model of fungal bronchopneumonia, myeloid-derived HIF-1α was shown to be critical for neutrophil recruitment and ultimately, survival of mice challenged with A. fumigatus CEA10 strain." (PMID 29375586, 2017).
Cachexia (1 paper, 2023). Severe weight loss, wasting of muscle, loss of appetite, and general debility related to a chronic disease. "We also observed that Caspase 1 gene expression increased in terminal cachexia, whereas Nod2 gene expression was increased only on T7, returning to basal levels in T14, whereas Nod1 and Hif‐1α gene expression did not change during the development of cachexia." (PMID 37177862, 2023).
calcific aortic valve disease (1 paper, 2021). "Aberrant expression of UBE2C leads to the degradation of pVHL (von Hippel-Lindau tumor suppressor), which increases HIF-1α levels, resulting in endothelial inflammation and epithelial-mesenchymal transition in calcific aortic valve disease." (PMID 34257576, 2021).
carcinoma in situ of oesophagus (1 paper, 2003). "HIF-1α immunoreactivity had already been identified in carcinoma in situ of oesophagus." (PMID 12966423, 2003).
cardiac interstitial fibrosis (1 paper, 2015). "On the other hand, cardiac interstitial fibrosis, which could be the result of a profibrotic state mediated by HIF-1α, does not seem to play a significant role in this model of CIH, as demonstrated in a previous study." (PMID 25738150, 2015).
cartilage disorders (1 paper, 2024). "Finally, resetting the circadian clock through interactions with HIF-1α and clock proteins presents a promising avenue for therapeutic interventions in cartilage disorders." (PMID 38534356, 2024). "We discuss different possible hypotheses describing the interplay between HIF-1α and the chondrocyte clock and offer some related therapeutic strategies in cartilage disorders such as OA." (PMID 38534356, 2024).
centronuclear myopathy (1 paper, 2022). Centronuclear myopathy (CNM) is an inherited neuromuscular disorder characterized by clinical features of a congenital myopathy and centrally placed nuclei on muscle biopsy. "They further related these findings to centronuclear myopathy, a disease in which HIF-1α is similarly elevated and neonatal myosin expression is maintained." (PMID 36453544, 2022). "The authors did, however, find such a phenotype in biopsy specimens of centronuclear myopathy (CNM), a disease that also includes abundant small immature fibers; immunostaining revealed large numbers of MYH8+ fibers as well as HIF-1α target gene expression." (PMID 36453544, 2022).
Cerebral arteriovenous malformation (1 paper, 2016). "Venous hypertension(VH) plays an important role in the pathogenesis of cerebral arteriovenous malformations (AVMs) and is closely associated with the HIF-1α/VEGF signaling pathway." (PMID 27869147, 2016).
cerebral astrocytoma (1 paper, 2017). An astrocytoma that arises from the cerebral hemispheres. "Recently, the value of HIF-1α has been reported to have a significantly positive correlation with the value of cellular density, while a significantly negative correlation with the value of apparent diffusion coefficient (ADC) in 34 patients with cerebral astrocytoma." (PMID 28418866, 2017).
cerebral malaria (1 paper, 2023). A sequestration of Plasmodium falciparum in the brain, which can cause coma and/or seizures. "Furthermore, insufficient expression of HIF-1α by brain cells has been suggested to contribute to the progression of cerebral malaria." (PMID 37375100, 2023). "Additionally, post-mortem brain tissue from severe cerebral malaria patients presented no changes in HIF-1α expression but increases in VEGFA, indicating changes in VEGFA may be tissue-dependent or HIF-independent." (PMID 37375100, 2023).
cerebral palsy (1 paper, 2023). A group of disorders affecting the development of movement and posture, often accompanied by disturbances of sensation, perception, cognition, and behavior. "In contrast, in the setting of chronic inflammation, as reported in children with cerebral palsy, HIF1α and HIF2α functions diverge markedly." (PMID 37546540, 2023).
cerebral small vessel disease (1 paper, 2024). Cerebral small vessel disease is the term currently used to pathological processes that affect the brain parenchymal circulation (arterioles, capillaries, and veins). "Although HIF1α did not modulate the expression of tight junction proteins, it might play a role in brain angiogenesis and underlie pathogenic mechanisms in Wnt/HIF1α signaling in diseases such as cerebral small vessel disease." (PMID 38147228, 2024).
cholangioma (1 paper, 2015). "While HIF-1α immunopositivity was limited in saline control livers, in DEN treated livers there was some cytoplasmic presence of the HIF protein in hepatocytes and cholangiocytes around the portal area, but immunopositivity was mostly observed in and around hepatocellular and cholangioma lesions." (PMID 25793288, 2015).
chondroblastic osteosarcoma (1 paper, 2024). An osteosarcoma characterized by the presence of atypical cartilage of variable cellularity. "Notably, HIF1A serves as the hallmark gene for hypoxia, and previous studies have reported that HIF1A, a critical gene within the hypoxia pathway, activates SOX9 as a transcription factor in chondroblastic osteosarcoma." (PMID 39033089, 2024).
chronic allograft nephropathy (1 paper, 2019). "However, profiling of biopsy tissues from chronic allograft nephropathy (CAN) patients showed significantly higher expression of both HIF-1α and TGF-β1 compared to the group without CAN." (PMID 29603016, 2019).
chronic asthma (1 paper, 2023). An asthma that is characterized by the development of persistent airway inflammation and recurrent attacks of breathlessness and wheezing, which vary in severity and frequency. "Thus, Lok may attenuate airway remodelling by inhibiting the PI3K-Akt/HIF-1α signaling pathway, thus alleviating chronic asthma airway epithelial EMT transformation." (PMID 37655452, 2023). "Besides, Lok may attenuate airway remodelling by inhibiting the PI3K-Akt/HIF-1α signalling pathway, thus alleviating chronic asthma airway epithelial EMT transformation." (PMID 37655452, 2023).
chronic liver failure (1 paper, 2022). Liver failure that develops slowly and gradually for some time, possibly for years, often as the result of cirrhosis, or malnutrition. "HIF-1α inhibitor rescued chronic liver failure through inhibiting cellular ROS production and mitochondrial dysfunction." (PMID 36164393, 2022).
chronic nasopharyngitis (1 paper, 2014). "The positive rates of HIF-1α and CAIX expressions in NPC were significantly higher than chronic nasopharyngitis (χ2 = 19.924, P < 0.01; χ2 = 11.985, P < 0.01)." (PMID 25377659, 2014). "The expression of HIF-1α and CAIX proteins was detected by immunohistochemical staining in 129 samples of NPC and 20 samples of chronic nasopharyngitis." (PMID 25377659, 2014). "Our results showed that the positive expression rates of HIF-1α and CAIX proteins in NPC were significantly higher than those in chronic nasopharyngitis (both P < 0.01)." (PMID 25377659, 2014). "While in 20 samples of chronic nasopharyngitis, no positive expression of HIF-1α was detected and there was 15 % (3/20) of sections with CAIX positive expression." (PMID 25377659, 2014).
clubfoot (1 paper, 2022). The most common congenital deformation of the foot, occurring in 1 of 1,000 live births. "We have detected an increase in HIF1A nuclear positivity in the contracted tissue of the relapsed clubfoot by means of IHC and also an increase in its mRNA expression, as detected by Real-time PCR." (PMID 35292718, 2022).
Cockayne syndrome B (1 paper, 2021).
colon polyps (1 paper, 2013). "Accordingly, our study indicated that estrogen reduced the expression of VEGF and HIF-1α in DMH-induced colon polyps." (PMID 24348555, 2013). "As ER beta was also the predominant ER subtype in the colon of rats, we hypothesized that estrogen might inhibit angiogenesis of colon polyps by downregulating HIF-1α and VEGF via ER beta." (PMID 24348555, 2013).
conjunctival intraepithelial neoplasia (1 paper, 2020). "Due to the similarity between cervical and conjunctival intraepithelial neoplasia, we focused on the markers HIF-1α and ProExC as potential diagnostic and prognostic markers of CIN." (PMID 32458097, 2020).
coronary atherosclerosis (1 paper, 2014). Atherosclerosis of the coronary vasculature. "In this cross-sectional study on asymptomatic type 2 diabetic subjects, we first evaluated the association between serum HIF-1α level and CAC, which is a good biomarker of the presence and amount of coronary atherosclerosis." (PMID 24564828, 2014).
craniopharyngioma (1 paper, 2022). A benign, partly cystic, epithelial tumor of the sellar region, presumably derived from Rathke pouch epithelium. "According to the DEGs and tissue immunofluorescence validation in our study, the expression of HIF-1α was significantly increased in the ACP tissue, consistent with the findings of a previous study, and HIF-1α seems to play a potential novel role in the biological process of the craniopharyngioma." (PMID 36091021, 2022).
cryptosporidiosis (1 paper, 2023). Intestinal infection with organisms of the genus Cryptosporidium. "In a neonatal rat model of cryptosporidiosis, cardiomyocytes have hyperexpression of HIF-1α; however, this finding is more suggestive of a link between gastroenteritis and cardiovascular disease than a direct induction of hypoxia by C. parvum." (PMID 37375100, 2023).
cystic tumors (1 paper, 2015). "An alternative explanation is that benign cystic tumors in patients with FH-deficiency may not have encountered enough of the “pseudohypoxic” stabilization of HIF-1α mediated upregulation of VEGF and GLUT1 to complete the transformation into cancerous lesions." (PMID 26380143, 2015).
dementia (1 paper, 2022). Loss of intellectual abilities interfering with an individual's social and occupational functions. "Once the mechanism of metabolite transfer via gap junction and activation of Hif1-α in brain is understood, this offers the potential to improve and develop novel therapies for dementia in the elderly whose main symptom is the disability of memory." (PMID 35185523, 2022).
demyelination (1 paper, 2015). "To determine whether HIF-1α regulates the onset and progression of inflammatory demyelination, we generated four different mouse strains with cell-specific genetic depletion or overexpression of HIF-1α in astrocytes and myeloid cells." (PMID 26213713, 2015).
diabetes insipidus (1 paper, 2016). A disorder characterized by excretion of large amounts of urine, accompanied by excessive thirst. "These diabetes insipidus phenotypes were completely absent in VhlΔ/ΔHif1aΔ/Δ mice but present in VhlΔ/ΔHif2aΔ/Δ mice, demonstrating that the constitutive stabilization of HIF-1α is the cause of constitutive diuresis." (PMID 27528422, 2016). "Taken together, our study characterizes a new mouse model for a form of diabetes insipidus and non-obstructive hydronephrosis and provides new insights into the physiological and pathophysiological effects of HIF-1α stabilization on the vasculature in the kidney." (PMID 27528422, 2016).